PINK1 (PTEN induced kinase 1)
Diseases named in the same sentence as PINK1 in open-access papers (continued):
Sharing a sentence is not in itself a finding about the gene and the disease.
cancer (continued). "In addition, PINK1 expression showed a potential inhibitory effect on the activity of the cell cycle (38%), apoptosis (22%) and DNA damage (22%) pathways in pan-cancer, further highlighting its potential role in inhibiting programmed cell death and contributing to tumor progression." (PMID 39859167, 2025). "However, emerging evidence indicates that PINK1 has roles in other human diseases, such as cancers." (PMID 39472438, 2024). "Also, PINK1 dysfunction is thought to be involved in cancers and other diseases in humans." (PMID 34800266, 2022). "Additionally, the mitophagy could be beneficial for radiosensitization of cancer depending on the Pink1/PARK2 pathway, and mitochondrial dysfunction and mitophagy have provided a new strategy for ROS sensitization." (PMID 34306311, 2021). "Whether PINK1 expression influences cancer patient survival remains unknown." (PMID 33244455, 2020). "We also verified that PINK1 might play a prognostic role across cancers." (PMID 33244455, 2020). "Notably, PINK1 expression was significantly correlated with nine cancer types." (PMID 33244455, 2020). "This might indicate that PINK1 plays a protective role across cancers." (PMID 33244455, 2020). "Because PINK1 regulates cancer cell survival, stress resistance, mitochondrial homeostasis, and cell cycle progression, it may serve as a therapeutic target or a predictive biomarker of response to treatment in cancer patients." (PMID 28060722, 2017). "Our pan-cancer analysis showed an improved survival in LUSC and KIRC patients with upregulated PINK1, indicating their potential prognostic value." (PMID 39859167, 2025). "We delved into the molecular mechanisms by which LC3, PINK1, PRKN, SRC, BNIP3L, BECN1, and OPTN regulate mitophagy, cancer progression and drug sensitivity or resistance." (PMID 39859167, 2025). "In cancer cells only, SHetA2 reduces calcium levels, mitochondrial length and fusion proteins, while inducing autophagy and PTEN-induced kinase 1 (PINK1)/PARKIN-mediated mitophagy." (PMID 40685746, 2025). "Significant changes in mRNA expression levels were identified across eight cancer types, with PRKN and PINK1 being generally downregulated and SRC being upregulated." (PMID 39859167, 2025). "Last, we gathered the IC50s of a wide variety of drugs among different cancer cell lines through the GDSC and CTRP databases and assessed the relationship between the mRNA values of MAP1LC3A, OPTN, SRC, BNIP3L, BECN1, PINK1, and PRKN and drug sensitivity." (PMID 39859167, 2025). "Overall, the Spearman’s correlation coefficients varied across different cancer types, revealing distinct patterns of immune cell correlation with the expression of OPTN, PINK1, MAP1LC3A, PRKN, BNIP3L, BECN1, and SRC." (PMID 39859167, 2025). "Among the potential therapeutic targets for these conditions are the mitochondrial protein PINK1 and GPR55 receptors, as the modulation of these has been shown to affect the progression of these cancers in various models." (PMID 40565152, 2025). "The analysis of CNVs in PRKN, OPTN, PINK1, SRC, BNIP3L, BECN1, and MAP1LC3A across various cancer types revealed significant heterogeneity in the types and frequencies of CNVs." (PMID 39859167, 2025). "Our findings indicate that the expression levels of CSNK2B, MTERF3, and PGAM5 are elevated in multiple cancers, while the expression levels of PINK1 and PRKN are reduced in several cancers." (PMID 38913914, 2024). "For example, ketoconazole induces apoptosis in cancer cells via COX-2 downregulation and PINK1–Parkin-mediated mitophagy activation." (PMID 39456203, 2024). "Also, the role of mitochondrial autophagy in cancer is complex and may influence cancer development through Parkin-PINK1-related signaling pathways and oxidative stress changes affecting cellular processes such as apoptosis, growth, proliferation, migration, and invasion." (PMID 38711526, 2024).
cancer (continued). "Dysregulation of mitophagy, involving proteins such as Parkin, PINK1, BNIP3, BNIP3L/NIX and p62/SQSTM1, further exacerbates tumour growth and metastasis by fueling cancer cell energy demands and enhancing cell survival through anti‐apoptotic pathways." (PMID 38534098, 2024). "In cancer cell lines, dissipation of MMP and increased oxidative stress have been shown to activate PINK1-Park on the OMM leading to mitophagy." (PMID 37098042, 2023). "Except for the typical PINK1/Parkin pathway, BNIP3, NIX and other receptor pathways can mediate mitophagy, inhibiting many cancers." (PMID 37610095, 2023). "Recent studies have shown that PINK1 activates AKT through the mTORC2/mitochondrial control axis to augment the aggressiveness of cancerous cell and accelerate the renewal of cancer stem cells through Notch signaling." (PMID 36909198, 2023). "As well-studied PINK1/Parkin-independent mitophagy receptor/adaptors, BNIP3 and BNIP3L/NIX have dual roles in cancer progression." (PMID 36831455, 2023). "PINK1 is a putative serine/threonine kinase, initially discovered as a gene governed by the tumor suppressor PTEN in cancer cells." (PMID 37940999, 2023). "Here, we discuss the roles that PINK1, Parkin, BNIP3, NIX, and FUNDC1 play in a wide array of cancers, clarifying the possible mechanisms of mitophagy in cancers." (PMID 36632220, 2023). "Moreover, inhibition of DRP1 prevents PINK1 accumulation and Parkin recruitment, accompanied by alleviation of mitochondrial dysfunction and anti-cancer efficiency in response to flubendazole treatment, suggesting that DRP1-mediated excessive mitophagy may lead to cell death." (PMID 35440104, 2022). "The mitochondrial PTEN-induced kinase-1 (PINK1) and the E3 ubiquitin ligase Parkin represent a protective mechanism by which cancer cells oppose the onset of mitochondrial apoptosis." (PMID 34360883, 2021). "PINK1 interacts with the oncogenic PI3K/Akt/mTOR signaling axis at multiple levels and controls the regulation of cancer survival and growth." (PMID 33981484, 2021). "PINK1 has been reported as a gene whose expression is increased by overexpression of PTEN, a representative tumor suppressor in cancer cells." (PMID 33912571, 2021). "The inhibition of PINK1–Parkin mediated mitophagy enhances the efficacy of the anticancer drug B5G1, a new derivative of betulinic acid, by inducing cancer cell death." (PMID 33375363, 2020). "There are some common pathogenetic factors shared by PD autosomal recessive Parkinsonism and some types of cancer, such as the proteins PARKIN, PINK1 (PTEN induced putative kinase-1), and DJ-1 (Parkinsonism associated deglycase)." (PMID 33066407, 2020). "However, the immunological and prognostic roles of PINK1 across cancers remain unclear." (PMID 33244455, 2020). "Mechanistically, PINK1 interacts with the pivotal oncogenic PI3-kinase/Akt/mTOR signaling axis and controls critical mitochondrial and metabolic functions that regulate cancer survival, growth, stress resistance and the cell cycle." (PMID 33615312, 2020). "Mitophagy can be regulated by different upstream regulators, such as PINK1, TRAP1, and Parkin, to induce cancer cell death." (PMID 32796618, 2020). "As mitophagy acts as “a double-edged sword” in cancer, we next investigated the interaction of B5G1-induced mitophagy and apoptosis in drug-resistant cancer cells using PINK1 siRNA, a mitophagy inhibitor, mdivi-1, and a lysosome inhibitor, Baf A1." (PMID 30850585, 2019). "PINK1 interacts with the pivotal oncogenic PI3K/Akt/mTOR signaling axis, mediating the critical mitochondrial and metabolic functions that regulate cancer survival, growth, stress resistance, and the cell cycle." (PMID 30595797, 2018). "In this review, we focus on the regulatory processes of proteins PINK1, PARKIN, and DJ-1 specifically during mitochondrial quality control due to its importance in cancer biology." (PMID 30274236, 2018).
cancer (continued). "Given its ability to inhibit the PI3K/AKT signaling pathway and to stimulate PINK1, PTEN is believed to prevent cancer progression." (PMID 30344951, 2018). "In cancer but also primary cells, sub-lethal doses of G-TPP activate all facets of PINK1- and Parkin-dependent mitoQC." (PMID 29290944, 2017). "PINK1 is ubiquitously expressed and was named due to induction by the tumor suppressor PTEN in cancer cells, drawing attention to its putative role in cancer from the first instance." (PMID 26973853, 2016). "Phosphatase and tensin homolog deleted on chromosome 10 (PTEN)-induced putative kinase 1 (PINK1), initially was identified as a downstream molecule of PTEN in cancer cells." (PMID 25108683, 2014). "Notably, PRKN exhibited the highest alteration frequency, affecting 34% of all cancer samples, followed by OPTN (21%), PINK1 (18%), SRC (15%), BECN1 (13%), MAP1LC3A (9%), and BNIP3L (5%)." (PMID 39859167, 2025). "Finally, with all the in silico and in vitro data obtained regarding the expression of PINK1 and GPR55 and their potential modulation in cancer models, we decided to compare these findings with data from public databases." (PMID 40565152, 2025). "Overall, these findings highlight the complex landscape of CNVs in PRKN, OPTN, PINK1, SRC, BECN1, BNIP3L, and MAP1LC3A across different cancer types, emphasizing the potential impact of these genetic alterations on cancer pathogenesis and the importance of considering CNVs in therapeutic strategies." (PMID 39859167, 2025). "For example, targeting PINK1 and PRKN to inhibit mitophagy could sensitize cancer cells to treatment by promoting the accumulation of dysfunctional mitochondria and enhancing oxidative stress." (PMID 39859167, 2025). "Additionally, key mitophagy receptors, such as PINK1, FUNDC1, or AMBRA1, when downregulated genetically, have been shown to sensitize cancer cells to chemotherapy." (PMID 40750884, 2025). "The rest of the genetic subgroups (SNCA or PINK1 carriers) accounted for just a small number of patients with a medical history of cancer; thus, they were not able to point to any particular cancer predisposition concomitant with harboring such mutations." (PMID 41300754, 2025). "Here, we conduct a comprehensive analysis of a mitophagy-related gene signature, composed of PRKN, PINK1, MAP1LC3A, SRC, BNIP3L, BECN1, and OPTN, across various cancer types, revealing significant differential expression patterns associated with molecular subtypes, stages, and patient outcomes." (PMID 39859167, 2025). "Targeting mitophagy-related genes like PINK1 and PRKN could potentially sensitize cancer cells to treatment by promoting the accumulation of dysfunctional mitochondria, thereby increasing oxidative stress and cell death." (PMID 39859167, 2025). "In addition to LRRK2, several other genes, e.g., α-synuclein, PTEN-induced kinase 1 (PINK1), F-box protein 7 (FBXO7), and ubiquitin C-terminal hydrolase L1 (UCHL1) show altered expression in cancer patients." (PMID 38612708, 2024). "Recent studies indicate that NET-treated cancer cells activate the mitochondrial biogenesis-related gene PGC1a and enhance the expression of fission- and fusion-related proteins, including DRP-1, MFN-2, PINK1, and Parkin." (PMID 39456203, 2024). "Over 200 genes can be modulated by Nrf2, including PINK1, whose transcription is upregulated under stress.NRF2 has recently been considered to be a key transcription factor of metabolic reprogramming in cancer cells." (PMID 36964576, 2023). "The interaction between PINK1 and PI3K-AKT has also been studied extensively in cancer." (PMID 37940999, 2023). "Moreover, PINK1-mediated phosphorylation of PTEN impaired the nuclear import of PTEN, thereby enhancing the cancer cells’ ability to resist chemotherapy and metastasize." (PMID 37940999, 2023). "PINK1 (PTEN-induced kinase 1) is a serine/threonine kinase that plays a crucial part in regulating various physiological and pathophysiological processes in cancer cells." (PMID 37940999, 2023).
cancer (continued). "Although Pink1 was initially identified as a gene upregulated in cancer cells, the specific role of Pink1 in tumorgenesis has not been fully understood yet." (PMID 35682755, 2022). "Interestingly, the classical PINK1‐Parkin pathway and mitophagy mediated by BNIP3/Nix and FUNDC1 in response to hypoxia are also involved in glycolytic metabolism in cancer cells." (PMID 36200262, 2022). "In addition to completely PINK1/parkin-independent mitophagy pathways, the ariadne-1 homolog in humans (ARIH1) promotes mitophagy in cancer cells independently of parkin but in a PINK1-dependent manner." (PMID 34688664, 2021). "Fortunately, we found three potential binding sites on PINK1 gene promoter for NFIB, and bioinformatics analysis revealed that PINK1 was enriched in focal adhesion and pathways in cancer." (PMID 33981484, 2021). "Notably, an E3 ubiquitin ligase ARIH1 highly expressed in cancer cells could trigger mitophagy in a PINK1-dependent and Parkin-defective way; this countered the chemotherapy-induced cell death in breast cancer and lung adenocarcinomas, eventually resulting in cancer cell resistance." (PMID 32587855, 2020). "Meanwhile, the correlations between PINK1 expression and the infiltration levels of B cells, CD8+ T cells, CD4+ T cells, macrophages, neutrophils and dendritic cells were significant in 13, 15, 20, 23, 15, and 21 cancer types, respectively." (PMID 33244455, 2020). "Therefore, it is reasonable to assume that PINK1 and PARK2 are potential prognosticators in this rare cancer subtype." (PMID 33139776, 2020). "None of the studies focused on the relationship between PINK1 expression and immune infiltration in cancer patients." (PMID 33244455, 2020). "The results showed that PINK1 was significantly correlated with six different immune infiltrates, B cells, CD8+ T cells, CD4+ T cells, macrophages, neutrophils and dendritic cells, across cancers." (PMID 33244455, 2020). "There is an interplay between DJ-1, PINK1, and PARKIN in cancer biology." (PMID 30274236, 2018). "The remaining genes are a part of several pathways involved in cancer etiology such as: Negative regulation of stress activated MAPK cascade (PBK and PINK1), intracellular signal transduction and regulation of autophagosome assembly (LRRK2 and PINK1) and RNA degradation (PABC3 and DDX6)." (PMID 29879995, 2018). "At gene level, Beclin-1, p-62, BNIP3, NIX/BNIP3L and TFEB mRNAs were not significantly modulated, while LC3B and PINK1 mRNA levels were increased and decreased, respectively, in cachectic cancer patients." (PMID 27459917, 2016). "Finally, as a result of their putative kinase function, PINK1 and LRRK2 are attractive potential targets in the treatment of PD and cancer even though their potential influence in tumour growth remains mostly indirect and suggestive thus far." (PMID 21203498, 2010). "In vitro studies, such as treating cancer cell lines with small-molecule inhibitors (e.g., SRC inhibitors like dasatinib or trametinib) or inducing mitophagy via PINK1 activators, could further elucidate the therapeutic relevance of these genes in overcoming drug resistance." (PMID 39859167, 2025). "Specifically, studies on mitophagy-related proteins, such as those involved in the PINK1/Parkin and BNIP3/NIX pathways, offer potential avenues to modulate mitophagy levels, thereby influencing tumor cell survival and proliferation, and providing new hope for cancer treatment." (PMID 39611141, 2024). "Unbalanced mitophagy may trigger or accelerate hepatocarcinogenesis, and a negative correlation exists between PINK1 with aggressive progression and poor prognosis of cancer in HCC specimens." (PMID 38299199, 2024). "Studies in human cancer cell lines have shown that dissipation of the mitochondrial membrane potential (MMP), increased oxidative stress or mitochondrial unfolded protein response (UPRmt) results in the stabilization of PINK1 on the outer mitochondrial membrane (OMM)." (PMID 37098042, 2023).
cancer (continued). "Therefore we examined whether phosphorylation by PINK1 could affect the nuclear transport of PTEN, thereby potentially promoting cancer metastasis and chemoresistance." (PMID 37940999, 2023). "There are no completed studies on the prognostic value of PINK1 across cancers." (PMID 33244455, 2020). "Furthermore, mitophagy suppression via knocking down key mitophagy receptors such as PINK1, FUNDC1 or AMBRA1 could chemo-sensitize cancer cells." (PMID 33280610, 2020). "There are not many studies on the expression of PINK1 in cancer." (PMID 33322704, 2020). "The consequences of PARK2 and PINK1 dysregulation in cancer are not fully elucidated." (PMID 33139776, 2020). "Conversely, the inability of cells to effectively divide in the absence of PINK1 has the potential to increased chromosomal aberrations, genetic instability and aneuploidy that could lead to cancer in some cell types." (PMID 26973853, 2016). "With regard to PINK1, m-RNA levels were significantly reduced in cachectic cancer patients with respect to controls and non-cachectic patients, whereas protein levels were not significantly modulated, although a trend toward increase in non-cachectic patients was observed." (PMID 27459917, 2016). "Interestingly, the restriction of PINK1-Parkin-mediated mitophagy by ANT3 knockdown increased the sensitivity of MM cells to BTZ, as controversy still exists over whether mitophagy benefits cancer development." (PMID 39744418, 2025). "However, the role of PINK1 in metastasis in different cancers has not yet been widely studied." (PMID 33244455, 2020). "ARIH1 is an E3 ubiquitin ligase widely expressed in numerous cancer cells that has also been demonstrated to ubiquitinate mitochondria to induce mitophagy in a PINK1- but not Parkin-dependent manner, which may contribute to chemotherapeutic resistance during cancer treatment." (PMID 32235615, 2020). "B5G1 induced ROS production and mitochondrial dysfunction, thereby triggering mitophagy in a manner dependent on PINK1 and Parkin but not Atg5 and Beclin 1, and mitophagy inhibition promotes B5G1-induced apoptosis in drug-resistant cancer cells." (PMID 30850585, 2019).